FAM227B (family with sequence similarity 227 member B)
Synonyms: C15orf33; FLJ32800
Tractability: No criterion of Open Targets' tractability assessment is met for any kind of drug.
Gene: Protein-coding gene on chromosome 15 (49,326,962 to 49,620,929, reverse strand). Ensembl gene ENSG00000166262.
Subcellular location (Human Protein Atlas): Nuclear speckles
Genetic constraint (gnomAD): Loss-of-function variants: 27 observed, 18.92 expected, observed/expected ratio (o/e) 1.43, 90% interval 1.05 to 1.87. The upper end of that interval is the gene's LOEUF score, 1.87, which puts it in group 6 of 6, group 1 being the genes least tolerant of losing a copy. Missense variants: 267 observed, 248.73 expected, observed/expected ratio (o/e) 1.07, 90% interval 0.97 to 1.19. Synonymous variants: 106 observed, 85.75 expected, observed/expected ratio (o/e) 1.24, 90% interval 1.05 to 1.45.
Homologues: Orthologues: chimpanzee FAM227B (98% identical), macaque FAM227B (96% identical), dog FAM227B (76% identical), pig FAM227B (74% identical), rabbit FAM227B (70% identical), rat Fam227b (60% identical), mouse Fam227b (59% identical), tropical clawed frog fam227b (32% identical).
Diseases named in the same sentence as FAM227B in open-access papers:
FAM227B is named in the same sentence as 7 diseases in open-access papers, as found by Europe PMC text mining. Sharing a sentence is not in itself a finding about the gene and the disease. The quoted sentences say what the papers report.
coronary artery disease (1 paper, 2026). "FAM227B showed a significant association signal with a specific clinical phenotype (e.g., coronary artery disease or hypertension) in the Cardiovascular category." (PMID 41570039, 2026).
hyperthyroidism (1 paper, 2026). Overactivity of the thyroid gland resulting in overproduction of thyroid hormone and increased metabolic rate. "FAM227B showed significant colocalization between hyperthyroidism-associated GWAS signals and its eQTL signals in adrenal gland (PP4 = 0.89), lung (PP4 = 0.85), and minor salivary gland (PP4 = 0.83)." (PMID 41570039, 2026). "Through integrated multi-omics analysis, this study is the first to characterize the bidirectional regulatory mechanism of PDE8B in hyperthyroidism and hypothyroidism, alongside the genetic associations of FAM227B and PDE10A with cardiovascular and neurological comorbidities." (PMID 41570039, 2026). "Through cross-validation of the four methods, 3 intersecting genes for hyperthyroidism (FAM227B, PDE8B, PDE10A) and 1 intersecting gene for hypothyroidism (PDE8B) were finally identified." (PMID 41570039, 2026). "Through cross-validation using four methods (SMR, TWAS, mBAT-combo, and PoPS), we identified three core candidate genes (FAM227B, PDE8B, PDE10A) associated with hyperthyroidism, with PDE8B as the sole intersecting gene showing significant association with hypothyroidism." (PMID 41570039, 2026). "Cross-validation by four methods identified FAM227B, PDE8B, and PDE10A as key genes for hyperthyroidism, and PDE8B as the critical gene for hypothyroidism." (PMID 41570039, 2026).
thyroid diseases (1 paper, 2026). "Meanwhile, through cross-tissue TWAS and multi-omics integration, we for the first time reveal the potential roles of FAM227B and PDE10A in thyroid diseases." (PMID 41570039, 2026).
cardiovascular diseases (1 paper, 2026). "PheWAS linked FAM227B to cardiovascular diseases and PDE10A to neurological pathways." (PMID 41570039, 2026).
neurological diseases (1 paper, 2026). "PheWAS results showed that FAM227B is significantly associated with cardiovascular phenotypes, that PDE8B is enriched in endocrine/metabolic pathways, and that PDE10A has strong genetic links to neurological diseases." (PMID 41570039, 2026).
FAM227B also shares sentences with these, for which no sentence is quoted: Hypertension (1 paper); hypothyroidism (1).